MTA3 (metastasis associated 1 family member 3)
Diseases named in the same sentence as MTA3 in open-access papers (continued):
Sharing a sentence is not in itself a finding about the gene and the disease.
tumor (continued). "MTA3 functions as a key negative regulator of EMT, suppressing tumor invasion and metastasis through transcriptional repression of Snail, thereby preserving E-cadherin expression." (PMID 41584603, 2025). "In summary, MTA3 is not only involved in regulating EMT and tumor metastasis but also functions as a reliable independent prognostic biomarker in AEG, facilitating the identification of high-risk patient populations." (PMID 41584603, 2025). "There is also evidence that KCNQ1 (potassium voltage-gated channel member), MTA3, and ZSWIM5 (zinc finger SWIM-type 5) have tumor suppressive roles." (PMID 31149338, 2019). "To study the relation between MTA3 and SOX2, we measured the (co-)expression of MTA3 and SOX2 in adjacent non-tumor tissues (ANT) and TSCC tissues from the 119 patients." (PMID 31552166, 2019). "Moreover, MTA3 was found to could inhibit tumor cell invasion and metastasis in these malignancies." (PMID 28418887, 2017). "Specifically, MTA3 may regulate the expression of major histocompatibility complex (MHC) molecules, facilitating immune evasion by tumor cells." (PMID 41584603, 2025). "Moreover, MTA3 colocalizes with the chromatin remodeling factor CHD5 in brain tissue, implicating it in neural development and tumor suppression." (PMID 41584603, 2025). "MTA3 has emerged as a molecule of growing interest due to its aberrant expression and functional significance in HCC, with accumulating evidence highlighting its critical role in tumor progression." (PMID 41584603, 2025). "At the molecular level, MTA3 directly represses transcription of Snail, a central regulator of EMT, thereby maintaining expression of the epithelial marker E-cadherin and inhibiting tumor cell invasion and metastasis." (PMID 41584603, 2025). "Altogether, our data suggest that MTA3 is capable of repressing TSCC CSC properties and tumor growth through downregulating SOX2 and MTA3low/SOX2high might be a potential prognostic factor for TSCC patients." (PMID 31552166, 2019). "Down-regulation of MTA3 mRNA and protein was detected in tumor tissues compared with non-tumor tissues; MTA3 levels were significantly lower in tumor cell lines with stronger metastatic potential compared with tumor cell lines with less metastatic potential." (PMID 28279208, 2017). "Immunoblot assay revealed that 72% tumor specimen had lower MTA3 protein expression than the paired adjacent noncancerous tissues (P<0.001)." (PMID 23671646, 2013). "MTA3 expression was decreased at both protein and mRNA levels in tumor tissues compared to the non-tumorous and lowed MTA3 levels were noted in tumor cell lines with stronger metastatic potential." (PMID 23671646, 2013). "No statistical difference was found between MTA3 overexpression and characteristics of aging (p = 0.1404), gender (p = 0.8683), tumor status (p = 0.1556), differentiation (p = 0.1985) and tumor type (p = 0.0604)." (PMID 23840517, 2013). "Notably, the MTA1, MTA2 and MTA3 components of the NuRD complex have been shown to play an important role in the ER and HER2 pathways regulating the epithelial-mesenchymal transition (EMT) and tumor cell invasion and metastasis, but they have distinct effects." (PMID 29625565, 2018).
metabolic disorders (1 paper, 2025). "More research is required to elucidate the long-term effects and underlying molecular mechanisms by which environmental toxins (arsenic and heavy metals) and metabolic disorders (diabetes and obesity) modulate MTA3 expression." (PMID 41584603, 2025).
MTA3 also shares sentences with these, for which no sentence is quoted: adenocarcinoma (3 papers); cardiovascular diseases (1); clear-cell renal cell carcinoma (1); gastric cancer (1); heart failure (1); immune dysfunctions (1); inflammatory bowel disease (1); insomnia (1); invasive carcinoma (1); lymphoma (1); nasopharyngeal carcinoma (1); pancreatic ductal adenocarcinoma (1).